Y_RNA (Y RNA )
Gene: Miscellaneous RNA gene on chromosome 5 (176,556,704 to 176,556,805, forward strand). Ensembl gene ENSG00000207420.
Homologues: Orthologues: chimpanzee Y_RNA (100% identical), macaque Y_RNA (93% identical), guinea pig Y_RNA (92% identical). Paralogues in human: Y_RNA (92% identical), Y_RNA (91% identical), RNY3 (90% identical), Y_RNA (89% identical), Y_RNA (88% identical), RNY3P1 (87% identical), RNY3P11 (87% identical), Y_RNA (87% identical), Y_RNA (86% identical), RNY3P14 (85% identical), RNY3P16 (85% identical), RNY3P4 (85% identical), and 98 more.